TRA2B (transformer 2 beta homolog)
Diseases named in the same sentence as TRA2B in open-access papers (continued):
Sharing a sentence is not in itself a finding about the gene and the disease.
tumor (14 papers, 2008 to 2025). "The TRA2B gene encoding Tra2β is amplified in particular tumours including those of the lung, ovary, cervix, stomach, head, and neck." (PMID 23935626, 2013). "Using antisense oligonucleotides to increase TRA2B PE splicing inclusion has been proposed as a potential therapeutic approach to reduce Tra2β protein‐coding transcripts and tumor growth." (PMID 41178187, 2025). "Another fusion is found with proximal breakpoints yielding fusion transcript SPATS2::TRA2B (21 tumor cells, 10%), and likely resulting from the same tumor genome rearrangements involving chr3 and chr12." (PMID 38464114, 2024). "A series of experiments performed herein confirmed that the proliferation, apoptosis and invasion of epithelial OC cells are significantly affected by disruption of TRA2B expression in tumor cells." (PMID 37547760, 2023). "The TRA2B gene is amplified in several tumor types, including lung, head and neck, ovary, stomach and uterus cancers." (PMID 32596243, 2020). "Based on the results regarding the TRA2B RASEs in OC transcriptome data from TCGA, TRA2B has the potential to regulate the cell cycle by influencing the AS patterns of related genes, a finding that enhances the knowledge of the molecular mechanisms by which TRA2B participates in tumor development." (PMID 37547760, 2023). "Zhang et.al demonstrated that bone mesenchymal stem cell (BMSC)-derived EVs could be transferred into OS cells to inhibit tumor progression by targeting transformer 2β homolog (TRA2B), before subsequently proposing the potential of miR-206 and TRA2B as novel therapeutic targets." (PMID 36555795, 2022).
infection (4 papers, 2015 to 2025). The state of being infected such as from the introduction of a foreign agent such as serum, vaccine, antigenic substance or organism. "The TRA2B PE splicing pattern switches again later in infection as antigen levels drop, with TRA2B PE splicing inclusion increasing as activated T cells switch to circulating memory T cells." (PMID 41178187, 2025). "As an upstream factor of innate immune activation, cellular alteration of TRA2-β concentration could be an early switch for alternative splicing in response to infection." (PMID 35127560, 2021). "One intriguing possibility is through the TRAF6-mediated K-63 ubiquitination and nuclear localization of hnRNPA1 during innate immune activation; if the activity of TRAF6 is inhibited during infection hnRNPA1 activity could drop, leaving TRA2-β pre-mRNA vulnerable to inclusion of the poison exon." (PMID 35127560, 2021). "However, infection of primary hippocampal neurons with a Tra2b-expressing lentivirus did not cause any change in TrkB isoforms expression." (PMID 31429825, 2019).
neurological disorders (3 papers, 2014 to 2025). "The reportedly altered expression and activity of TRA2B has been directly implicated to major neurological disorders, such as AD and PD, as well as to promoting tau hyperphosphorylation." (PMID 35292653, 2022).
neurodegenerative disease (1 paper, 2025). A disorder of the central nervous system characterized by gradual and progressive loss of neural tissue and neurologic function. "Alzheimer’s Disease (AD): TRA2β also plays a role in the progression of AD, a neurodegenerative disease mainly marked by the accumulation of amyloid-β (Aβ) plaque in the brain." (PMID 41009380, 2025). "Dysregulation of TRA2β in vivo has been shown to lead to several neurodevelopmental disorders and neurodegenerative diseases in humans and animal models." (PMID 41009380, 2025). "Therefore, differential alternative splicing of TRA2β influences the development of structural systems within the brain, and its dysregulation may contribute to neurodegenerative disease development and scattered neuronal structures." (PMID 41009380, 2025).
neurodevelopmental disorder (1 paper, 2025). A behavioral and cognitive disorder with onset during the developmental period that involves impaired or aberrant development of intellectual, motor, or social functions. "A notable but unnamed neurodevelopmental disorder is marked by an aberrant increase in a truncated TRA2β isoform known as TRA2β-S." (PMID 41009380, 2025).
TRA2B also shares sentences with these, for which no sentence is quoted: age-related macular degeneration (2 papers); cholangiocarcinoma (2); frontotemporal dementia (2); Parkinson disease (2); bladder carcinoma (1); chronic lymphocytic leukemia (1); colon adenocarcinoma (1); colorectal cancer (1); corticobasal degeneration (1); dementia (1); ductal carcinoma (1); endometrial cancer (1); gynecological cancer (1); head and neck cancer (1); hematological malignancies (1); hepatocellular carcinoma (1); idiopathic pulmonary fibrosis (1); Intellectual disability (1); left ventricular noncompaction (1); leukemia (1); metabolic syndrome (1); microcephaly (1); neuroblastoma (1); ovarian tumors (1); Parkinsonism (1); portal hypertension (1).